MMP13 (matrix metallopeptidase 13)
Diseases named in the same sentence as MMP13 in open-access papers (continued):
Sharing a sentence is not in itself a finding about the gene and the disease.
melanoma (45 papers, 2008 to 2025). A malignant, usually aggressive tumor composed of atypical, neoplastic melanocytes. "Specifically, in melanoma, high MMP-13 levels are associated with metastasis and reduced patient survival." (PMID 41471689, 2025). "To evaluate RUNX2 association with CXCR4 in melanoma cells, we started by detecting the expression of these two markers and the matrix metalloproteinase 13 (MMP13) invasiveness marker in several melanoma cell lines." (PMID 38474372, 2024). "In line with this, in several human cancers including melanoma, MMP13 is associated with metastasis and poor survival." (PMID 39202425, 2024). "Here we found that MMP-13 was associated with metastasis and poor survival in 79 patients with melanoma." (PMID 25749207, 2015). "Furthermore, MMP-13 expression in melanoma cells has been linked to increased migratory activity and epithelial–mesenchymal transition marker expression." (PMID 41471689, 2025). "Indeed, MMP-13 has been associated with metastasis and poor survival in patients with primary melanoma." (PMID 30800067, 2019). "Our data also show that MMP-13-caused VE-cadherin degradation on melanoma cells could lead to release of β-catenin into the cytoplasm and nucleus; nuclear β-catenin may thus activate MMP-13 transcription and form a positive feedback loop to amplify β-catenin signaling." (PMID 25749207, 2015). "As anticipated, ArcA treatment resulted in decreased protein and mRNA levels of both MMP-9 and MMP-13 across all melanoma cell lines." (PMID 39948552, 2025). "This impact of AP2ε on the migratory phenotype is supported by other recent findings, demonstrating that AP2ε regulates the expression of genes involved in melanoma invasion and metastasis, like matrix metalloproteinases (MMP13) in non-melanoma cells." (PMID 38773108, 2024). "In human melanoma tissue samples, a positive correlation has been observed between MMP-13 expression and metastatic activity." (PMID 39769318, 2024). "Although YBX1 binds to the AP-1 site in the MMP13 promoter and represses its expression in HeLA cells, shYBX1-silenced A375 melanoma cells had a significant reduction in the expression of MMP13." (PMID 36672165, 2023). "Another collagenase, MMP-13, is increased during melanoma invasion, and its stromal expression is required for melanoma vascularization." (PMID 35558554, 2022). "Based on an in vivo study, stromal derived MMP-13 (a collagenolytic enzyme) is also required for melanoma metastasis." (PMID 34207884, 2021). "MMP1 is interstitial collagenases, initially, detected in highly invasive malignant melanoma together with MMP13." (PMID 29320405, 2018). "Because the YB-1 silenced cell strains also had a knockdown of MMP13 expression, this role was supported by another study done on A375 melanoma cells, where RNAi of MMP13 resulted in a similar cell cycle arrest in G1/G0." (PMID 29320405, 2018). "MMP‐14 and its downstream effector MMP‐2 are major players in angiogenesis and tumorigenesis, and MMP‐13 promoted tumor angiogenesis, melanoma invasion, and metastasis." (PMID 27932444, 2017). "MMP-13 also cleaves VE-cadherin to bind to β-catenin, forming a complex that inhibits β-catenin translocation, thus inhibiting VM and melanoma invasion." (PMID 27034014, 2017). "We found that melanoma cells with up-regulated MMP-13 expression promoted invasion of tumor cells through Matrigel compared with control cells transfected with empty vector." (PMID 25749207, 2015). "MMP-13 was located in the cytoplasm of tumor cells, with strongly positive staining at the invasive front of melanoma." (PMID 25749207, 2015). "We also performed both an ectopic up-regulation and a short hairpin RNA (shRNA) knockdown of MMP-13 in melanoma cell lines." (PMID 25749207, 2015). "Our evidence suggests that MMP-13 is positively correlated metastasis and short survival in melanoma patients, but negatively regulates VM formation in melanoma." (PMID 25749207, 2015).
melanoma (continued). "This study demonstrated that MMP-13 has dual effects on melanoma: promotion of metastasis and disruption of formation of VM patterns." (PMID 25749207, 2015). "In conclusion, we have shown that increased MMP-13 expression in melanoma has two effects: promotion of metastasis and disruption of VM formation." (PMID 25749207, 2015). "From human melanoma tissue samples, we found a positive correlation between MMP-13 expression and metastasis." (PMID 25749207, 2015). "About twice as many A375 and B16-F10 melanoma cells incubated with MMP-13-digested collagen II, III, IV, aggrecan or laminin-5 invaded the transwell membrane as untreated controls." (PMID 25749207, 2015). "We examined MMP-13–Ln-5 cleavage fragments to explore their mechanism for increased invasiveness in melanoma, and compared them with MMP-2–Ln-5 γ2 cleavage products, which reportedly also induce tumor cell invasiveness." (PMID 25749207, 2015). "This study investigated the role of MMP-13 in the metastasis and VM formation of melanoma using human melanoma tissue samples and cell lines." (PMID 25749207, 2015). "Given that MMP13-specific inhibitors have already been developed, this study supports the evaluation of these inhibitors for the treatment of melanoma." (PMID 25749207, 2015). "By contrast, knocked down MMP-13 expression in melanoma cells induced tumor cells to form more typical ECM-rich vessel-like networks." (PMID 25749207, 2015). "In conclusion, MMP-13 has a dual effect in melanoma, as it promotes invasion and metastasis but disrupts VM formation." (PMID 25749207, 2015). "Recent studies support involvement of MMP13 in tumor angiogenesis during melanoma progression and skin carcinoma." (PMID 22253746, 2012). "Human MMP-13 and MMP-1 are also linked to cutaneous malignancies, such as SCC, and melanoma, which involve inflammation, stromal cell activation, and angiogenesis in the tumor micro-environment." (PMID 22880047, 2012). "The effects of host-derived MMP-13 on lung metastasis were examined by comparing the metastases in the lungs 3 weeks after injecting B16BL6 mouse melanoma cells into tail veins of MMP-13 KO and WT mice." (PMID 22015555, 2011). "Our study has demonstrated that the expression of MMP-13 within the lung tissue is dramatically upregulated on day 1 after the intravenous injection of melanoma cells in WT mice." (PMID 22015555, 2011). "Our results suggest that MMP-13 is overproduced by endothelial cells in the lungs with melanoma cells and has a protective role in lung metastasis by local generation of endostatin." (PMID 22015555, 2011). "Nevertheless, it is plausible that enhanced production of endostatin on days 1 and 3 after the melanoma cell injection is due to the proteolytic action of MMP-13." (PMID 22015555, 2011). "To the best of our knowledge, we have provided the first evidence that lung metastases of B16BL6 melanoma cells are increased in MMP-13 KO mice after intravenous injection, indicating a protective role for MMP-13 in melanoma cell lung metastasis." (PMID 22015555, 2011). "The expression level of MMP-13 mRNA and protein in the lung tissues after intravenous injection of melanoma cells was monitored by RT–PCR and immunoblotting." (PMID 22015555, 2011). "In summary, the data in the current study have suggested that endostatin generated by the action of MMP-13 in the lung tissue is involved in reduced lung metastases of melanoma cells." (PMID 22015555, 2011). "The expression of MMP-13 in WT mouse lung tissue was stimulated on day 1 after intravenous injection of the melanoma cells and MMP-13 was immunolocalised to vascular endothelial cells in the lungs." (PMID 22015555, 2011). "Lung metastases of mouse melanoma B16BL6 cells were analysed in MMP-13 knockout (KO) and wild-type (WT) mice after intravenous injection." (PMID 22015555, 2011).
melanoma (continued). "Although matrix metalloproteinases (MMPs) are implicated in tumourigenesis and cancer progression, the role of MMP-13 in melanoma cell metastases is poorly understood." (PMID 22015555, 2011). "In future studies, we will investigate the effect of specific MMP13 inhibitors in animal melanoma models." (PMID 20667128, 2010). "A functional role for stromal MMP13 in melanoma development was recently described in a MMP13-/- mouse model." (PMID 20667128, 2010). "Our data show for the first time that growth stimuli are mediated via MMP13 in melanocytes and melanoma, suggesting an autocrine MMP13-driven loop." (PMID 20667128, 2010). "In summary, these data indicate that MMP13 plays an important role in the growth factor-induced proliferation of melanocytes and melanoma cells as well as in the dedifferentiation of melanocytes." (PMID 20667128, 2010). "Together with our data, it appears that tumor cell - or stroma-derived MMP13 plays a role in several processes of melanoma development." (PMID 20667128, 2010). "Given that MMP13-specific inhibitors are already developed, these results support the evaluation of these inhibitors in the treatment of melanoma." (PMID 20667128, 2010). "Conducted research indicates that MMP-13 may serve a dual function in melanoma, promoting both metastasis and the disruption of vasculogenic mimicry (VM)." (PMID 39769318, 2024). "The pharmaceutical actions of Rg3 on the inhibition of MMPs were: MMP2 in six cell lines (originated from lung, thyroid, nasopharynx, colorectum, and bone tumor), MMP9 in four cell lines (lung, thyroid, nasopharynx, and bone tumor), and MMP13 in the B16F10 melanoma cell line, respectively." (PMID 36012338, 2022). "Additionally, we found that USMB-shMincle significantly inhibited CXCR4 and MMP-13 expression in both human melanoma and lung cancer mouse models." (PMID 34589582, 2021). "Melanoma associated fibroblast are also able to remodel the ECM by MMP-1, MMP-2, MMP-13, and MT1-MMP (MMP-14) secretion, which could influence the motility and invasiveness of melanoma cells." (PMID 32984031, 2020). "Our data show that treatment with naproxen-HBTA in mice with cutaneous melanoma was able to reduce the expression of MMP-2 and MMP-13 in tumor tissues confirming the efficacy of naproxen-HBTA in inhibiting the metastatic potential of B16F10 melanoma cells and the metastasis initiation in mice." (PMID 30800067, 2019). "YBX1 silencing is reported to significantly reduce MMP13 expression in melanoma cells." (PMID 31358880, 2019). "Therefore, identification of other co-partners (transcription factors) or novel binding sequences within MMP13 gene promoter is crucial to determine the mechanism of YB-1 interference with collagenases MMPs expression in melanoma cells." (PMID 29320405, 2018). "MMP-13 is reported to be involved in the invasive VGP of melanomas." (PMID 27271600, 2016). "MMP-13 has broad substrate specificity, and its expression has been found to promote tumor progression and metastasis in a variety of tumors, including melanoma." (PMID 25749207, 2015). "Furthermore, stroma-derived MMP13 was found to be involved in the growth of liver, lung, brain and heart metastases of melanoma cells." (PMID 25880591, 2015). "However, this study also investigated the mechanism through which MMP-13 promotes invasion and metastasis of melanoma cells." (PMID 25749207, 2015). "Although much research remains to be done, our results indicate that MMP-13 may be used as a biomarker or therapeutic target in melanoma." (PMID 25749207, 2015). "Furthermore, stroma-derived MMP13 was recently found to be involved in the growth and organ-specific metastasis of melanoma." (PMID 22253746, 2012). "In addition, our data have demonstrated that restoration of the endostatin levels at the early stage of lung metastases (on days 1–4 after the intravenous melanoma cell injection) leads to a significant reduction of the metastases in MMP-13 KO mice." (PMID 22015555, 2011).
melanoma (continued). "In the present study, we aimed to examine the role of host-derived MMP-13 in the development of lung metastases of mouse B16BL6 melanoma cells by focusing on the extravasation step after the intravenous injection of cells into the MMP-13 KO and wild-type (WT) mice." (PMID 22015555, 2011). "Since our metastasis model reflects mainly the ability of melanoma cells to extravasate from blood vessels, the reduced melanoma cell metastases in WT mice may be ascribed to decreased extravasation by endostatin formation with MMP-13 in the lung tissue." (PMID 22015555, 2011). "However, in breast carcinomas and melanomas, MMP-13 is reportedly expressed almost exclusively by stromal fibroblasts and/or endothelial cells within or near the tumours." (PMID 22015555, 2011). "In addition, lung metastases of melanoma cells in MMP-13 KO mice were reduced by intraperitoneal administration of endostatin." (PMID 22015555, 2011). "Importantly, MMP13 was also found to be necessary for the proliferation of the human melanoma cell line A375." (PMID 20667128, 2010). "However, the role of MMP13 in mediating melanocyte and melanoma cell proliferation as described in this manuscript is in line with emerging non-classical MMP functions in outside-in signalling and cell cycle control." (PMID 20667128, 2010). "MMP2 was found to be expressed in samples of human melanoma-associated spongiform scleropathy, whereas MMP13 could not be detected in this study." (PMID 33966129, 2021). "However, the exact function and possible mechanism of MMP-13 in melanoma metastasis remains unknown." (PMID 25749207, 2015). "As MMP13 also plays a role for melanoma progression and specific inhibitors are already developed, it might be considered as a target for the treatment of MMP13-sensitive melanoma." (PMID 20667128, 2010). "Prominent MMPs, including MMP-1, MMP-2, MMP-3, MMP-9, MMP-13, and MMP-14, have been shown to significantly contribute to the development of melanoma." (PMID 39769318, 2024). "The expression of RUNX2, MMP13 and CXCR4 at the protein level was also verified in the same melanoma cell lines." (PMID 38474372, 2024). "Several matrix metalloproteinases are expressed in melanoma, the tumor, and the peritumoral stroma, including MMP-1, MMP-2, MMP-9, MMP-13, and MMP-14." (PMID 35558554, 2022). "DHA reduces the migration/invasion of melanoma by down-regulating several matrix metalloproteinases, such as MMP-2 and MMP-13, which are involved in melanoma invasion." (PMID 34069297, 2021). "The inhibition or blockade of soluble molecules responsible for promoting metastasis in melanoma, including MMP1, MMP2, and MMP13 is another approach." (PMID 34207884, 2021). "Collagenolytic enzymes as MMP-13 and MMP-14 are involved in melanoma development where they mediate the vascularization of tumors or tumor cell migration during tissue invasion." (PMID 32906814, 2020). "In tissue homogenate of subcutaneous melanoma excised from NAP-HBTA treated-mice we found a significant reduction of both MMP-2 and MMP-13 proteins compared to control mice." (PMID 30800067, 2019). "Our data demonstrate that MMP13 links growth-stimulatory signals such as EGF and FCS to cell cycle progression in melanocytes and melanoma cells and to dedifferentiation in melanocytes." (PMID 20667128, 2010). "Melanoma cells express a number of various types of MMPs such as MMP-1, MMP-2, and MT1-MMP which have essential parts in melanoma vasculogenic mimicry formation and MMP-13 which promotes invasion and metastasis." (PMID 30800067, 2019). "Because MMP3 activates the collagenases MMP1, MMP8 and MMP13 that are capable of degrading collagen types I, II, III, V and IX as well as native fibrillary collagen which is crucial for melanoma metastasis, we tested for MMP3 secretion by performing western blot analyses." (PMID 31728131, 2019).
melanoma (continued). "Collagenases, MMP-1, MMP-8, and MMP-13, are the dominant extracellular proteinases with the ability to cleave native fibrillar collagen types I, II, III, and V. As they can degrade dermal collagen, they are particularly relevant in melanoma." (PMID 27271600, 2016). "Stromal expression of MMP-13 has been implicated in angiogenesis of malignant melanoma and cutaneous SCC and lack of MMP-13 was reported to reduce vascular density of wound granulation tissue." (PMID 22880047, 2012). "However, MMP-13 is known to be expressed by vascular endothelial cells in and around the tumour masses of B16F1 melanoma cells implanted in the mouse dermis and in the branches of pulmonary arteries of mice exposed to cigarette smoke." (PMID 22015555, 2011). "In addition to MMP-2, CAFs secrete other proteolytic enzymes, including MMP-1, MMP-13, and MMP-14, which sustain melanoma invasion by leading to ECM digestion and formation of “tracks”, that melanoma cells use to move through the tumor mass and eventually leave the primary site." (PMID 34067929, 2021). "While MMP-13 replenishment increased tumor metastasis by promoting angiogenesis, MMP-13 inactivation inhibited stromal-promoting melanoma metastasis, indicating that the interactions of tumor and stromal cells might be an important issue for MMP-13 participating in metastasis." (PMID 26528698, 2015). "MMP-13 expression correlated with melanoma thickness and diameter, but not with patient age or sex." (PMID 25749207, 2015). "For example, a study analyzing the expression of MMPs in melanoma found that MMP-1, MMP-2, MMP-3, MMP-7, MMP-9, and MMP-13 showed increased levels in melanoma tissues compared to normal tissues." (PMID 39200315, 2024). "After immunohistochemical (IHC) staining of MMP-13 in melanoma tissues, 36 of 79 tumors were found to have high MMP-13 expression (MMP-13high) in tumor cells, whereas 43/79 tumors (including 11 with negative staining) had low MMP-13 expression (MMP-13low)." (PMID 25749207, 2015).